FGF21 (fibroblast growth factor 21)
Diseases named in the same sentence as FGF21 in open-access papers (continued):
Sharing a sentence is not in itself a finding about the gene and the disease.
type 2 diabetes (continued). "Circulating FGF21 levels have been found to be elevated in patients and experimental animals with various metabolic conditions, such as obesity, non-alcoholic fatty liver disease, and type 2 diabetes." (PMID 32922298, 2020). "Moreover, increased circulating FGF21 levels have been observed in cases of obesity, type 2 diabetes, or nonalcoholic fatty liver disease, which suggests its protective effects against various metabolic disorders." (PMID 33277568, 2020). "Accordingly, exercise-induced FGF21 secretion is impaired in patients with type 2 diabetes." (PMID 31546675, 2019). "Therefore, FGF21 is currently considered as a therapeutic option but also as a predictive marker for the development of type 2 diabetes." (PMID 30927227, 2019). "Therefore, we investigated the effect of FGF21 on endothelial function in both type 1 and type 2 diabetes." (PMID 31511499, 2019). "In contrast to the lack of association with type 2 diabetes, our data provide evidence for the putative effects of FGF21 on several clinically important metabolic traits, including blood pressure, ACR in the urine, and higher LDL cholesterol." (PMID 29641994, 2018). "In accordance with these observations, FGF21 has been found to prevent hepatic steatosis and atherosclerosis and, furthermore, it has been shown to have therapeutic potential against metabolic diseases, such as type 2 diabetes." (PMID 29444136, 2018). "The lack of an association between the human FGF21 allele and type 2 diabetes strengthens the inference for the lack of any anti-diabetic properties." (PMID 29641994, 2018). "Whether FGF21 induces preventive effect on type 2 diabetes-induced cardiomyopathy was investigated in the present study." (PMID 29445083, 2018). "However, under various stress conditions, FGF21 is increased, for example, in individuals who either are overweight or have type 2 diabetes, or NAFLD." (PMID 29854743, 2018). "Animal studies have shown that FGF-21 ameliorates hyperglycemia, hyperlipidemia, and insulin resistance, and may thus prevent the development of type 2 diabetes." (PMID 29021814, 2017). "In conclusion, we observed a strong, dose-dependent association between serum FGF-21 levels and increased risk of incident type 2 diabetes in Chinese women but not in men." (PMID 29021814, 2017). "This has to led the hypothesis that a rise in serum FGF21 levels may be a predictor for metabolic syndrome and type-2 diabetes and that these may be states of relative “FGF21-resistance”7." (PMID 28256636, 2017). "Furthermore, prospective cohort studies in type 2 diabetes have shown that the circulating FGF21 level is a marker of rapid CKD progression, remaining significant even after adjustment for the baseline glomerular filtration rate." (PMID 28582462, 2017). "Consistent with the previously reported ability of FGF21 administration to improve hyperglycaemia and enhance insulin sensitivity and glucose clearance, we observed a protection from type 2 diabetes and beta cell loss independent of body fat." (PMID 28770320, 2017). "FGF21 is emerging as a potential human therapeutic agent for the treatment of type 2 diabetes." (PMID 26872145, 2016). "Moreover, we detected a strong association of FGF21 with carotid IMT in women as well as iliac IMT in men and women with type 2 diabetes." (PMID 26047614, 2015). "The serum FGF21 levels in patients with NAFLD or type 2 diabetes were also within the range." (PMID 26441837, 2015). "In type 2 diabetic rat models, FGF21 administration ameliorates inflammation biomarkers." (PMID 26441837, 2015). "In conclusion, serum FGF21 levels independently and positively connect with LEAD in Chinese women with type 2 diabetes after adjusted for the traditional risk factors, and its gender difference may be due to the difference of estrogen levels." (PMID 25850006, 2015).
type 2 diabetes (continued). "Elevated serum FGF21 levels have been shown in subjects with coronary heart disease (CHD) and was associated with both carotid atherosclerosis in women and carotid artery plaques in type 2 diabetes subjects." (PMID 26047614, 2015). "Plasma FGF21 was also found to elevate in type 2 diabetic or impaired glucose tolerance patients." (PMID 24900988, 2014). "Since HIV patients with lipodystrophy share the same metabolic disturbances as subjects with type 2 diabetes we aimed to determine whether muscle FGF-21 mRNA is altered in these patients." (PMID 23533568, 2013). "In addition, FGF21 has a powerful therapeutic potential for the treatment of type 2 diabetes in rodents and monkeys." (PMID 23667629, 2013). "As FGF21 therapy normalizes blood glucose in animal models of type 2 diabetes, the induction of hepatic FGF21 by metformin might play an important role in metformin's antidiabetic effect." (PMID 23118742, 2012). "In animals models of type 2 diabetes treatment with recombinant FGF21 lowers blood glucose, corrects dyslipidemia, and increases energy expenditure, which makes FGF21 an attractive pharmaceutical target for treatment of type 2 diabetes." (PMID 23118742, 2012). "Another long-acting FGF21 variant, PF-05231023, induced a body weight loss, an improvement in plasma lipoprotein profile and in adiponectin levels in overweight/obese subjects with type 2 diabetes, without effects on blood glucose." (PMID 36500979, 2022). "Similarly, treatment of type-2 diabetes patients with fenofibrate elevated FGF21 serum levels." (PMID 34095143, 2021). "In addition, activation of FGF21 pathway may correlate with the effect of SGLT2 inhibitors on protecting the renal function in type 2 diabetes and delaying progression of CKD." (PMID 34675822, 2021). "Recently, a synthetic FGF21 variant, LY2405319, has been shown to reduce low-density lipoprotein (LDL) cholesterol and triglyceride levels, increase adiponectin levels, improve fasting insulin levels, and induce weight loss in obese patients with type 2 diabetes." (PMID 33588950, 2021). "Although the roles of Serpina11, Cdh16, Lrrc27, and Lrrc66 in regulating islet function remain unclear, Acod1 is known to be important in modulating the immune system and mitochondrial function, and Fgf21 can protect against type 2 diabetes in mice by increasing insulin expression and secretion." (PMID 32527043, 2020). "Moreover, a previous report has shown that reduced dietary protein may retard the development of type 2 diabetes or insulin resistance in high-fat-diet-induced obese mice and New Zealand obese mice, possibly through induction of FGF21." (PMID 29507597, 2018). "Thus, it would appear that despite elevated baseline FGF-21 levels (“FGF-21 resistance”), obese individuals with type 2 diabetes may still benefit from administration of an FGF-21 analog." (PMID 26441838, 2015). "A regulatory mechanism involving a cooperative interaction between insulin and glucagon may have evolved to allow for the induction of FGF21 gene expression during a broad range of stress conditions including starvation and diseases arising from overnutrition (e.g. type 2 diabetes)." (PMID 24733293, 2014). "While caution must be exercised due to the single case nature of the data, the fact that LY remained partially efficacious in an animal at the late stage of disease development opens the possibility that FGF21 based therapy may have therapeutic utility in patients with well advanced type 2 diabetes." (PMID 23823755, 2013). "Thus, the robust effects of MR on FGF21 could possibly explain, at least in part, the protection against type 2 diabetes in HFD mice." (PMID 23236485, 2012). "In conclusion, our study revealed pivotal contributions of TGF-alpha, FGF-21, hGDNF, and CX3CL1 in the advancement of type 2 diabetes and its complications." (PMID 38606083, 2024).
type 2 diabetes (continued). "Circulating FGF21 levels are typically elevated in conditions of impaired metabolic health, such as obesity, non-alcoholic fatty liver disease (NAFLD) and type 2 diabetes (T2DM)." (PMID 36501091, 2022). "Our results support previously reported associations between the FGF21 rs838133 variant with macronutrient and alcohol intake, lipid levels, blood pressure, waist-to-hip ratio, and liver enzymes as well as the lack of association with type 2 diabetes in the UK Biobank cohort." (PMID 33946944, 2021). "Therefore, elevated FGF21 levels may be a predictor for metabolic syndrome and type 2 diabetes." (PMID 32372975, 2020). "Administering FGF21 analogue significantly increases HDL-C and reduces triglycerides in obese human subjects with type 2 diabetes or hypertriglyceridaemia." (PMID 31885672, 2019). "FGF21 was demonstrated to counteract the injury induced by elevated and oxidized LDL cholesterol concentrations in rodents and patients with type 2 diabetes." (PMID 30157856, 2018). "Clinical research has shown that serum FGF21 levels are higher in subjects who are overweight/obese and have NAFLD or type 2 diabetes." (PMID 29854743, 2018). "Fibroblast growth factor 21 (FGF-21) is mainly secreted by liver and has been reported to be involved in the pathogenesis of type 2 diabetes." (PMID 29021814, 2017). "The anti-diabetic activities observed in animal models also appear to apply to humans, as the FGF-21 analog LY2405319 improves the lipoprotein profile and lowers glucose in obese patients with type II diabetes." (PMID 26962859, 2016). "In this study, we assessed the relationship between circulating FGF21 and carotid, femoral and iliac intima-media thickness (IMT) as well as subclinical atherosclerosis in patients with newly diagnosed type 2 diabetes." (PMID 26047614, 2015). "Serum FGF21 may be one of the strong predictors for various kidney diseases including the progression of CKD and the hard renal outcomes in type 2 diabetes patients, but more large-scale clinical research are needed to confirm this finding." (PMID 37009852, 2023). "Consistent with the hypothesis, FGF21 was greatly higher in the patients suffering from renal diseases and high FGF21 increased the incidence of CKD disease and the renal outcomes in type 2 diabetes patients." (PMID 37009852, 2023). "In contrast, plasma FGF21 was not significantly altered in Alzheimer's disease or type 2 diabetes compared to healthy aging controls." (PMID 36642986, 2023). "FGF-21 plays an important role in the treatment of type 2 diabetes, while FGF-21 has the advantage of no obvious side effects, such as edema and hypoglycemia." (PMID 34721299, 2021). "Despite extensive efforts by global pharmaceutical companies to develop FGF21 analogues, several clinical trials failed to produce positive outcomes for the treatment of type 2 diabetes and its related metabolic disorders." (PMID 33277568, 2020). "Treatment of engineered recombinant FGF21 (LY2405319) for 1 month has been tested for its improvement of LDL-C, HDL-C, triglycerides, body weight, blood adiponectin, and β-hydroxybutyrate levels in obese patients with type 2 diabetes." (PMID 30842736, 2019). "FGF19 and FGF21 are also considered as predictors of development of some diseases, for example, type 2 diabetes, non-alkoholic fatty liver disease, atherosclerosis, coronary artery disease, and chronic kidney disease." (PMID 30927227, 2019). "Further, in vitro and in vivo studies indicated that FGF21-induced cardiac protection against type 2 diabetes was mainly attributed to lipotoxicity rather than glucose toxicity." (PMID 29445083, 2018). "Increased FGF21 levels and elevated energy expenditure do not protect against hyperglycaemia and type 2 diabetes per se." (PMID 29550873, 2018). "In a population of African males with or without type 2 diabetes, FGF-21 portrays a similar pattern in the circulation as previously reported in Asian and European populations." (PMID 30298107, 2018).
type 2 diabetes (continued). "In line with our mouse data, we found hypermethylation of four CpG sites annotated to FGF21 in adipose tissue of subjects with type 2 diabetes compared with non-diabetic controls." (PMID 29091029, 2017). "Serum FGF21 level independently and positively links LEAD in Chinese women with type 2 diabetes." (PMID 25850006, 2015). "Thus, FGF21 is a potential drug candidate for diseases, such as NAFLD, dyslipidemia, and type 2 diabetes." (PMID 26441837, 2015). "The aim of the study was to assess serum fibroblast growth factor 21 (FGF21) concentrations in Chinese type 2 diabetic patients with and without retinopathy and to assess the association between FGF21 and the severity of retinopathy." (PMID 24895642, 2014). "Paradoxically, circulating FGF-21 is increased in obese nondiabetic subjects and in newly diagnosed type 2 diabetes, where it correlates positively with adiposity and fasting insulin." (PMID 23533568, 2013). "Fibroblast growth factor 21 (FGF21) plays an important role in the regulation of energy homeostasis during starvation and has an excellent therapeutic potential for the treatment of type 2 diabetes in rodents and monkeys." (PMID 23667629, 2013). "Similarly, fibroblast growth factor 21 (FGF21) analogs, such as pegbelfermin, have progressed into clinical development, showing beneficial effects on lipid metabolism, insulin sensitivity, and hepatic steatosis in obese individuals with type 2 diabetes." (PMID 40699742, 2025). "Our findings indicated that TGF-α and CX3CL1 exhibited a positive correlation with the genetically predicted susceptibility to T2D, and elevated concentration of FGF-21 and hGDNF could mitigate the risk of developing T2D, while type 2 diabetes did not exert a significant influence on them." (PMID 38606083, 2024). "The first hypothesis is that FGF21-based therapies will not have beneficial effects on type 2 diabetes." (PMID 29641994, 2018). "However, baseline FGF21 levels were not reported to be associated with CVD mortality in the FIELD study, probably because the subjects of that study were type 2 diabetes patients only." (PMID 28821258, 2017). "Besides, excessive protein consumption may induce negative outcomes (such as type-2 diabetes) by overstimulating the mTOR (mechanistic target of rapamycin) signaling pathway and concurrently inhibiting the FGF21 (fibroblast growth factor 21) signaling pathway." (PMID 38649521, 2024). "In addition, β-cell-specific knockout of β-klotho (coreceptor of FGF21) led to impaired glucose-stimulated insulin secretion (GSIS) and glucose intolerance in mice, while adenovirus-mediated β-klotho overexpression alleviated the defect of islet GSIS in type 2 diabetic mice." (PMID 37576954, 2023). "However, no changes in circulating FGF21 have been observed after eight weeks of endurance training in obese nondiabetic men or after 10 weeks of either resistance or aerobic training in overweight women with type 2 diabetes." (PMID 31546675, 2019). "Pharmacological administration of recombinant FGF21 increases energy expenditure, glucose tolerance, and insulin sensitivity and decreases adiposity, hyperlipidemia, and hepatic triacylglycerol accumulation in rodent and non-human primate models of obesity and type 2 diabetes." (PMID 24733293, 2014). "So far, no data are available on direct administration of native FGF-21 to humans; however, a FGF-21 analog (LY2405319) has shown promise in obese human subjects with type 2 diabetes." (PMID 26441838, 2015).
Hepatic steatosis (270 papers, 2010 to 2026). Steatosis is a term used to denote lipid accumulation within hepatocytes. "Previous data have identified an increase in mRNA FGF21 expression associated with hepatic steatosis in humans." (PMID 41373582, 2025). "Despite these challenges, elevated FGF-21 levels have been shown to consistently decrease hepatic steatosis, and improve IR in metabolic disorders caused by high-fat diets." (PMID 40437610, 2025). "This research confirmed the reliable analytical and clinical performance of the FGF21 ELISA kit, reinforcing its potential as a diagnostic biomarker of hepatic steatosis." (PMID 40563517, 2025). "Therapeutics focusing on FGF21 have been of particular interest as up-regulation in FGF21 has been linked to progression of fatty liver disease." (PMID 40943823, 2025). "For example, upregulation of FGF21 has been observed as a compensatory mechanism in hepatic steatosis associated with long-term alcohol exposure." (PMID 39409124, 2024). "The liver-specific transcription factor CREBH also contributes to the upregulation of FGF21 transcription and is implicated in the control of hepatic steatosis." (PMID 39211324, 2024). "FGF21-deficient mice fed a KD gained weight and developed hepatic steatosis, whereas control mice exhibited weight loss and reduced fatty liver." (PMID 38609395, 2024). "Utilizing a liver-specific KLB knockdown mouse model, we further confirmed this association, highlighting the profound impact of KLB deficiency in limiting KD’s improvement of hepatic steatosis, suggesting the indispensability of the liver FGF21-KLB pathway." (PMID 38609395, 2024). "Increased circulating FGF21 levels promote weight loss, enhance energy expenditure, improve glucose homeostasis and insulin sensitivity, alleviate fatty liver disease, and stimulate fat breakdown." (PMID 39100807, 2024). "In rodent models of diet-induced nonalcoholic hepatitis (NASH), FGF-21 deficiency exacerbates hepatic steatosis, inflammation, and fibrosis, while FGF-21 supplementation attenuates these pathological changes and reduces NASH markers level." (PMID 37288111, 2023). "Increased plasma levels of the hepatokine Fibroblast Growth Factor 21 (FGF-21) are associated with hepatic steatosis, but low levels of FGF-21 are associated with advanced fibrosis/cirrhosis in patients with CHB." (PMID 37312098, 2023). "In contrast, FGF21-deficient mice exhibited significantly more weight gain, developed hepatic steatosis, and demonstrated adipose lipolysis disfunction when fed alcohol." (PMID 37432218, 2023). "In human and animal trials, the administration of FGF21 induces weight loss via the leptin pathway and it seems to have favorable effects on lipid and on glucose metabolism and fatty liver disease via decreased lipogenesis and inflammation." (PMID 37685811, 2023). "In particular, the development of fatty liver has been reported to promote the secretion of hepatokine such hepassocin, fetuins A and B and fibroblast growth factor 21 (FGF21), that are also involved in causing liver inflammation." (PMID 35874657, 2022). "In the liver, the SIRT1-mediated activation of FGF21 prevented liver steatosis caused by fasting, indicating the possible relationship between sirtuins and FGF21." (PMID 34368135, 2021). "Among these is Fgf21, which is secreted from the liver and promotes weight loss and improves glucose tolerance and hepatic steatosis." (PMID 34023388, 2021). "This suggests that Ahnak deficiency improves hepatic steatosis largely through enhanced expression of FGF21 and genes associated with fatty acid oxidation." (PMID 33785868, 2021). "We recently found that the plasma levels of CSF‐1, OSM, and FGF‐21 are significantly associated with hepatic steatosis (Lovric et␣al, 2018)." (PMID 34694070, 2021).